INS (insulin)
Diseases named in the same sentence as INS in open-access papers (continued):
Sharing a sentence is not in itself a finding about the gene and the disease.
diabetes (continued). "We also found no racial and ethnic difference in diabetes treatment with oral agents, insulin, or both." (PMID 16776886, 2006). "Approximately 75% of participants were taking oral diabetes medications, 29% were taking insulin, and 12% were taking no diabetes medication." (PMID 16776894, 2006). "Each interview had as its main aim to obtain the person's perspective on the problems faced by people with diabetes in the given country in gaining access to insulin and proper diabetes care, rather than seeking precise statistical information." (PMID 16504123, 2006). "In January 2006, the first inhaled human insulin (INH, Exubera® (insulinhuman [rDNA origin])InhalationPowder) was approved for use in adult patients with type 1 diabetes mellitus (T1DM) or type 2 diabetes mellitus (T2DM) in the United States and European Union." (PMID 16901335, 2006). "The effect of race/ethnicity was independent of age, insulin use, education, intensity of physician visits, or diabetes education." (PMID 16716235, 2006). "Furthermore, the importance of insulin and IGF-I signaling in human diseases, such as diabetes and cancer, ensure that each new finding will have important ramifications for human health, notably that of the elderly." (PMID 16441841, 2006). "Diabetes mellitus is a chronic condition whose onset is given when the pancreas does not produce enough amount of insulin or when the body does not manage to effectively use the produced insulin." (PMID 16446918, 2005). "Other proteins tested in similar experiments involved detection of tubulin from human plasma and insulin and leptin from diabetes serum samples (data not shown)." (PMID 16281978, 2005). "By definition (see Methods section), none of these subjects had a self-report history of diabetes, and none reported taking insulin or diabetic pills to lower blood sugar." (PMID 15918903, 2005). "Since insulin/IGF-I levels and PKC activity are altered in diabetes, we speculate that abnormalities in TRPV1 function may contribute to neuropathy in diabetes." (PMID 15857517, 2005). "For NAG, there was an interaction between urinary cadmium and diabetes (insulin-treated vs. other diabetics and nondiabetics; regression coefficients (β): diabetics = 2.3, nondiabetics = 0.8; R2 = 0.10; p = 0.042)." (PMID 16263522, 2005). "In patients with diabetes mellitus and without myocardial ischemia, infusion of insulin and glucose increased the contractile force, i.e. rest LVEF and LVEF during dynamic exercise measured by radionuclide ventriculography." (PMID 15932638, 2005). "This fundamental question has not been addressed by previous studies with (pro)insulin producing hepatocytes as diabetes in these models was induced chemically rather than by autoimmune means." (PMID 15679918, 2004). "Two groups of bank voles were analyzed for diabetes, pancreas histology, autoantibodies to glutamic acid decarboxylase (GAD65), IA-2, and insulin by standardized radioligand-binding assays as well as antibodies to in vitro transcribed and translated Ljungan virus antigens." (PMID 12745669, 2003). "In people with diabetes, the pancreas does not produce sufficient insulin (type 1 diabetes) or the body does not respond appropriately to the insulin (type 2 diabetes)." (PMID 15706798, 1998). "Insulin resistance does not immediately lead to overt diabetes, because the patient’s pancreatic beta cells initially can increase their insulin production enough to compensate for the insulin resistance." (PMID 15706798, 1998). "Five children (8%) had pathogenic variants that do not cause syndromic diabetes (GCK [n = 2], HNF1A [n = 1], INS [n = 1], and the PTF1A enhancer [n = 1]); thus, these additional features are likely to be coincidental and unrelated to the monogenic diabetes diagnosis." (PMID 40746173, 2026).
diabetes (continued). "The KD had divergent effects: it normalised fetal growth in the mild diabetes group by preventing beta cell proliferation and premature maturation, thereby reducing insulin secretion, but failed to rescue IUGR in the severe diabetes group, despite partially restoring beta cell function." (PMID 42265456, 2026). "Moreover, in one study of 12 healthy male adults without diabetes, intact soya protein significantly elevated the two-hour area under the curve (AUC) of both insulin (p=0.018) and glucagon (p<0.001) compared to hydrolyzed soya protein." (PMID 41602572, 2026). "PEI was not isolated to individuals with PNDM; individual 12, who had biochemically confirmed PEI, had transient diabetes that was diagnosed at birth and was not insulin treated between the ages of 3 months and 5 years, despite requiring enzyme replacement therapy for PEI during this same period." (PMID 41500078, 2026). "Ever use of metformin, insulin, sulfonylureas, DPP‐4 inhibitors, and SGLT‐2 inhibitors was associated with worse overall survival compared to patients who did not develop prediabetes/diabetes." (PMID 41287203, 2026). "We isolated islets from individuals without diabetes undergoing partial pancreatectomy, previously characterized for glucose tolerance, insulin sensitivity, and insulin secretion, using laser capture microdissection, and analyzed them via high-performance liquid chromatography-mass spectrometry." (PMID 41854718, 2026). "This suggests that the instructions may not effectively enhance overall diabetes knowledge possibly due to the complexity of insulin regimens hindering users’ ability to fully process the information." (PMID 41311517, 2026). "It includes basic details like age, pregnancy count, body mass index, and skin-fold thickness; vital signs such as blood pressure; lab results related to blood sugar (fasting glucose and insulin); the Diabetes Pedigree Function; and a simple yes/no label for Type-2 diabetes." (PMID 41624303, 2026). "However, there remains uncertainty over its role in clinical care of diabetes that is not completely insulin-dependent, particularly type 2 diabetes (T2D)." (PMID 41355468, 2026). "According to specialist care nurses for patients with diabetes, patients with T1DM are often newcomers, those who are newly diagnosed, or those with years of evolution who require ongoing education on the management of their condition, including insulin administration and carbohydrate counting." (PMID 41564321, 2026). "The finding that deletion of JNK1 prevented the impairment of insulin secretion and β cell survival induced by proinflammatory cytokines suggests that targeting JNK1 and JNK2 in β cells could be a new therapeutic approach for diabetes." (PMID 41480766, 2026). "Two further individuals were in diabetes remission and not receiving insulin treatment." (PMID 41500078, 2026). "This case illustrates that even elderly patients with very long-standing T2D may achieve sustained insulin withdrawal in the context of comprehensive ILI, underscoring the importance of integrating lifestyle medicine into diabetes care to reduce polypharmacy and enhance long-term outcomes." (PMID 42158779, 2026). "A detailed history was taken for the duration and complications of diabetes, and samples were drawn for fasting and postprandial blood sugar levels, HbA1c, LFT (liver function test) and KFT (kidney function test), lipid profile, serum fasting insulin levels, and serum apelin levels." (PMID 42211608, 2026). "While physical activity is known to improve metabolic health, its effectiveness in preventing diabetes-induced muscle atrophy, particularly in the absence of insulin, remains unclear." (PMID 42164254, 2026). "Controlling glucose levels using non‐insulin antihyperglycemic medications rather than insulin in patients with cancer may prevent diabetes progression and the subsequent need for insulin administration." (PMID 41287203, 2026).
diabetes (continued). "The population was stratified based on three mechanisms related to diabetes pathophysiology: insulin secretion (fISR and IGI to estimate insulin secretion at fast and during the first phase of the OGTT), resistance (HOMA‐IR), and fasting insulin clearance (fIC) that reflects mainly hepatic IC." (PMID 41133433, 2026). "It appears that both children in this review had diabetes for a significant period of time, that they had no insulin secretion at the point of admission to the congregate care facilities and were completely dependent on external insulin sources that had to be administered by their caregiver." (PMID 41597086, 2026). "Diabetes is a chronic disease, characterized by elevated blood sugar levels resulting from insufficient insulin production or a lack of the body’s response to insulin." (PMID 41601933, 2026). "Type 2 diabetes mellitus (T2DM), the most prevalent type of diabetes, affects more than 38 million individuals in the United States (approximately 1 in 10) and is defined by chronic hyperglycemia and insulin resistance, which refers to a reduced cellular response to insulin." (PMID 40819304, 2026). "In the present case, although ketosis at the time of diabetes diagnosis was not confirmed, the patient initially responded to oral hypoglycemic agents and did not require insulin therapy for at least four months after diagnosis, despite being positive for anti-GAD antibodies." (PMID 41476905, 2026). "The 3 most common types of diabetes include type 1 diabetes (T1D), in which the pancreas does not produce insulin; type 2 diabetes (T2D), in which body cells become resistant to insulin over time; and finally, gestational diabetes, which occurs during pregnancy." (PMID 40424579, 2025). "Moreover, WFS1 is likely to be involved also in type 2 diabetes mellitus (T2DM), as islets from T2DM donors had significantly lower levels of WFS1 and insulin gene expression than islets from donors without diabetes." (PMID 40988749, 2025). "It has also been proposed that zinc is involved in the etiology of type 2 diabetes mellitus (T2DM) due to its significant role in glucose metabolism, especially in the synthesis, storage, and secretion of insulin as well as the conformational integrity of insulin in its hexameric form." (PMID 39941463, 2025). "The concept of looking at the effect of liver transplantation on glucose anti‐glycaemic agent (namely insulin) requirements and glycaemic control in patients with pre‐existing diabetes has not been reviewed on a large scale before, making the study concept novel." (PMID 40664615, 2025). "Despite advancements in insulin formulation, delivery devices and glucose monitoring, most patients with Type 1 (T1D) and Type 2 (T2D) diabetes remain dependent on exogenous insulin or small-molecule drugs that treat symptoms rather than the underlying cellular and genetic dysregulations." (PMID 41226304, 2025). "In Japan, where over 70% of individuals with diabetes are aged 65 or older and often exhibit a non-obese phenotype with impaired insulin secretion, dipeptidyl peptidase-4 inhibitors remain a cornerstone therapy due to their ability to enhance insulin secretion without increasing hypoglycemia risk." (PMID 40607140, 2025). "This may explain why normoglycemic patients develop postoperative diabetes less frequently than prediabetic patients, who may not experience the same compensatory increase in insulin sensitivity." (PMID 40205383, 2025). "Given that WHO uses venous plasma glucose for diabetes diagnosis, whereas FAO and WHO accept both capillary and venous glucose for glycemic index testing, our results underscore the importance of selecting appropriate measurement methods when assessing insulin sensitivity and glycemic responses." (PMID 40509433, 2025).
diabetes (continued). "Results indicated that AI-DSS was non-inferior to physician-led adjustments in time in range and insulin dose adjustments, with no diabetes-related adverse events reported in the AI-DSS group (compared to two cases of severe hypoglycemia and one DKA event in the physician group)." (PMID 40502401, 2025). "However, larger, long, clinical trials in which insulin therapy is compared to other diabetes therapies simply do not support any such adverse effects." (PMID 40035222, 2025). "Finally, those persons with NF1 who were diagnosed with diabetes mellitus type 1 appear to require less insulin when compared with sibling and non-sibling controls." (PMID 40279245, 2025). "This discrepancy may be explained by differences in experimental design, as TRIM72's negative effects on insulin signaling appear to be specific to models of severe diabetes." (PMID 41000062, 2025). "Moreover, IRS-1 KO mice exhibit growth retardation and their peripheral tissues become insulin-resistant or have reduced insulin sensitivity; however, the condition does not progress to diabetes because of a compensatory increase in insulin secretion." (PMID 39859555, 2025). "Existing treatments, such as insulin therapy and wound dressings, may not adequately address the multifaceted nature of chronic wounds in diabetes." (PMID 40280905, 2025). "However, we have noted that the prevalence of diabetes is similar in the Kyushu–Okinawa Population Study to that in the FOS, but the BMI levels are much lower, as are the insulin levels and HOMA-IR, and there is a higher prevalence of low HOMA-β in Japan as compared to the FOS." (PMID 40218874, 2025). "Although pregnancy itself is widely considered a diabetogenic state in nature, the dysfunctional regulation of insulin fetuses, as well as other metabolic regulatory hormones in patients with diabetes, endangers the patient and fetus as opposed to patients who can properly regulate these hormones." (PMID 40868219, 2025). "Typical features include young onset of hyperglycemia (before 25 to 30 years of age), absence of diabetes autoantibodies, absence of insulin resistance, residual beta cell function that persists during follow-up, and family history of early-onset diabetes in a first-degree relative." (PMID 39717432, 2025). "However, these metrics were not available in the Look AHEAD dataset, and diabetes duration and insulin use were more practical." (PMID 40707395, 2025). "Speculatively, we believe that the differences in the association of CGM‐derived metrics with MASLD among adults and adolescents with T1DM might be due to some factors, such as diabetes duration, prevalence of MASLD, prevalence of overweight/obesity and time of exposure to insulin therapy." (PMID 40083078, 2025). "However, the effect of aerobic exercise on interstitial glucose concentration (IG) has not been reported in dogs with insulin-treated naturally-occurring diabetes mellitus." (PMID 40612145, 2025). "Approximately 95% of individuals with diabetes have T2D, whether or not they are also resistant to insulin." (PMID 40507585, 2025). "The PAUSE app’s user flow designs support the diverse needs of patients (ie, patients with chronic conditions needing SDMG and their caregivers), providing tailored experiences for different groups, including individuals with no diabetes, and those managing diabetes with or without insulin therapy." (PMID 41308191, 2025). "The use of cyclosporin rather than tacrolimus and a reduction in total steroid exposure have been shown to reduce the incidence of NODAT and the requirement for insulin post-transplant, and a rapid steroid withdrawal was found to reduce insulin requirements though not the diabetes prevalence." (PMID 40566549, 2025). "In addition, according to observational and experimental data, DPP4 inhibitors, sulfonylureas, and insulin, are unlikely to slow cognitive decline beyond the benefits of glycemic control in diabetes without dementia." (PMID 41420258, 2025).
diabetes (continued). "Even though the literature has not yet come to a consensus on whether or not insulin per se is involved in restenosis, the consensus is that insulin therapy is the expression of more advanced or worse-controlled diabetes." (PMID 40978996, 2025). "Median diabetes duration was longer in those with versus without diabetic retinopathy, and a higher proportion of those with versus without diabetic retinopathy were on treatment with metformin and/or insulin." (PMID 40745009, 2025). "Additionally, PDCD1 did not correlate with time since diabetes diagnosis, INS, or GCG, suggesting a lack of a direct link between islet hormone depletion and PD-1–mediated immune modulation." (PMID 40244011, 2025). "IDE, originally known as the main enzyme involved in the cleavage of insulin as well as other amyloidogenic peptides, such as the β-amyloid (Aβ) peptide, eliminates Aβ’s neurotoxic effects, one of the hallmarks of Alzheimer’s disease (AD), which shows the relationship between IDE, diabetes, and AD." (PMID 40943177, 2025). "The beneficial effects observed in pancreatic tissues, including reduced levels of pro-inflammatory cytokines and enhanced insulin secretion, suggest that swimming may be a promising non-pharmacological intervention for managing diabetes and its complications." (PMID 41154214, 2025). "Lachnospirales were identified as the cause of substantial increases in plasma glucose and reduced serum insulin in colonized germ-free mice; however, no study has reported the direct effect of this species on the synthesis or metabolism of testosterone in type 2 diabetes mellitus patients." (PMID 40256744, 2025). "Furthermore, in all animal strains evaluated, we showed the same increase in the blood glucose levels and a similar decrease in plasma insulin levels, suggesting glycemic stability in our model of diabetes independent of used rats or different strains of mice." (PMID 40496562, 2025). "The 2022 Management of Hyperglycemia in Hospitalized Adult Patients in Non-Critical Care Settings guideline by the Endocrine Society recommends the use of rt-CGM in conjunction with confirmatory bedside POC-BG testing in insulin-treated diabetes patients admitted with noncritical illness." (PMID 40893589, 2025). "Three had type 2 diabetes mellitus, but none was insulin dependent." (PMID 40429470, 2025). "Since the majority of patients with type 2 diabetes mellitus do not lack insulin but rather are resistant to insulin action, agents improving metabolic profile (management of obesity with drugs, including GLP-1 agonists) in addition to drug therapy to control blood glucose are used." (PMID 40001508, 2025). "In children and adolescents, data remain limited and fragmented, with studies varying in population characteristics, diagnostic criteria, and reported outcomes, and some relying on older cohorts from eras when insulin therapy and diabetes management were not comparable to current standards." (PMID 41346657, 2025). "They found that women with different timelines of diabetes onset (before, during, and after the menopausal transition) all exhibited lower β-cell function and insulin sensitivity during the period of menopausal transition compared with women who did not develop diabetes." (PMID 40941437, 2025). "Studies indicate that patients without obesity with diabetes have impaired insulin secretion or decreased insulin sensitivity compared with patients with obesity; however, the precise lifestyle and molecular mechanisms that cause diabetes in patients without obesity remain to be fully elucidated." (PMID 40074175, 2025). "Therefore, the treatment strategy for diabetes is no longer just to deal with late complications of diabetes but to prevent the further deterioration of insulin resistance in advance." (PMID 40362436, 2025).